MSH6 (mutS homolog 6)
Diseases named in the same sentence as MSH6 in open-access papers (continued):
Sharing a sentence is not in itself a finding about the gene and the disease.
hepatocellular carcinoma (4 papers, 2021 to 2023). A malignant tumor that arises from hepatocytes. "In Liu’s study, the CT genotype of MSH6 (rs1042821) reduced the risk of primary hepatocellular carcinoma (PHC)." (PMID 37035153, 2023).
lung adenocarcinoma (4 papers, 2020 to 2023). A carcinoma that arises from the lung and is characterized by the presence of malignant glandular epithelial cells.
lymph node metastasis (4 papers, 2021 to 2024). "Molecular-pathological analysis indicated that low expressions of MSH6 and MLH1 as measured by immunohistochemistry were potential risk factors for 253 lymph node metastasis." (PMID 34082744, 2021). "Univariate analysis of the risk factors for 253 lymph node metastasis showed that CEA, tumour max diameter, presence of vessel carcinoma embolus, number of harvested lymph nodes and MSH6- and MLH1-expression levels were associated with 253 lymph-node metastasis." (PMID 34082744, 2021). "Univariate analyses revealed the following risk factors for 253 lymph node metastasis: high preoperative levels of CEA, large tumour max diameters, and numbers of harvested lymph nodes, presence of vessel carcinoma emboli, low level of MSH6 and MLH1 immunohistochemical staining intensity." (PMID 34082744, 2021). "The immunohistochemical intensities of MSH6 and MLH1 in the 253 lymph-node metastasis patient group were significantly higher than those in patients without lymph-node metastases (78.9% + 13.1% vs. 68.0% + 26.1%, P = 0.013; 72.5% + 15.6% vs. 56.5% + 24.3%, P = 0.002)." (PMID 34082744, 2021).
metastatic disease (4 papers, 2020 to 2023).
pancreatic adenocarcinoma (4 papers, 2021 to 2022).
pituitary adenoma (4 papers, 2017 to 2025). "To define the prognostic value of MSH6 deficiency for prediction of recurrence and invasiveness in pituitary adenomas, we evaluated the MSH6 status in the present series." (PMID 28900805, 2017). "The aim of this study was to assess the prognostic value of MGMT and MSH6 immunoexpression for aggressive functioning pituitary adenomas." (PMID 28900805, 2017). "In a first small series of aggressive pituitary adenomas and carcinomas retrospectively tested for MSH6 status, the positive response to TMZ treatment corresponded to a high immunoexpression of MSH6." (PMID 28900805, 2017). "MGMT (O6-methyl-guanine-DNA methyltransferase) and MSH6 (mutS homolog 6) immunoexpression have been linked to the response to TMZ treatment and MGMT immunoexpression has been additionally linked to early recurrence of non-functioning pituitary adenomas." (PMID 28900805, 2017). "From our observation that low-to-moderate MGMT immunoexpression correlates with early recurrence in non-functioning pituitary adenomas, the aim of the current study was to investigate the status of MGMT and MSH6 immunoexpression in a consecutive series of recurrent functioning macroadenomas." (PMID 28900805, 2017).
pituitary tumor (4 papers, 2018 to 2023). A benign or malignant neoplasm affecting the pituitary gland. "Genomic sequencing of the pituitary tumor (before chemotherapy) and liver metastasis (after chemotherapy) showed evidence of alkylating chemotherapy-induced somatic mutations with the presence of a MSH6 mutation in the TMZ-treated liver metastasis." (PMID 33112279, 2021). "To determine whether MSH6 expression affects pituitary tumor growth and PD-L1 expression, we investigated the effect of gene ablation of MSH6 on PD-L1 expression and cell proliferation in AtT-20ins and GH3 cells." (PMID 32325698, 2020). "To examine the association between MSH6/2 and PD-L1 mRNA expressions and MIB-1-labeling index (LI), an indicator of pituitary tumor growth, we performed simple linear regression analysis and compared the expression levels of each gene in the MIB-1 < 3% group and ≥ 3% group." (PMID 32325698, 2020). "In molecular mechanisms such as innate immune resistance, the results of this in vitro investigation suggests that PD-L1 may be downregulated by decreased MSH6 expression in pituitary tumors, which could lead to a tumor microenvironment that facilitates tumor immunity in pituitary tumors." (PMID 32325698, 2020). "Alternatively, pituitary tumors are generally classified as being benign, including the series in the current study, so there may be a regulatory mechanism in MSH6/2 and PD-L1 mRNA expressions in benign tumors as NFPAs that differs from that in malignant tumors." (PMID 32325698, 2020). "Based on these findings, we hypothesize that MSH6/2 and PD-L1 expressions could affect pituitary tumor proliferation, and invasion by pathological classification of NFPAs and ICIs may be effective for NFPA subtypes with decreased MSH6/2 expression and increased PD-L1 expression." (PMID 32325698, 2020). "Regarding pituitary tumors, in one case report, the ICIs ipilimumab and nivolumab were effective against a pituitary carcinoma with negative expression of MSH6." (PMID 32325698, 2020). "Therefore, MSH6 and MGMT immunoexpression analysis has been proposed in the morphologic study of pituitary tumors." (PMID 29963012, 2018).
squamous cell carcinoma (4 papers, 2020 to 2025). A carcinoma arising from squamous epithelial cells.
atypical endometrial hyperplasia (3 papers, 2020 to 2025). An endometrial hyperplasia characterized by cytologic and architectural changes which may lead to endometrial carcinoma.
bladder urothelial carcinoma (3 papers, 2019 to 2023). "The mOS of the MSH6− group is prolonged compared with that of the MSH6+ group in patients with bladder urothelial carcinoma (P = 0.015)." (PMID 31151482, 2019).
breast invasive ductal carcinoma (3 papers, 2022 to 2025). "They observed frequent promoter hypermethylation of BRCA2, CDH13, MSH6, PAX5, PAX6, and WT1 genes in both DCIS and adjacent invasive ductal adenocarcinoma lesions." (PMID 40131297, 2025).
cardiomyopathy (3 papers, 2016 to 2019). A disease of the heart muscle or myocardium proper. "A 38-year-old male who was initially enrolled in the NCGENES study for cardiomyopathy was found to have a 27 kb whole gene deletion of MSH6 (hg 19, chr2:48010242–48037615)." (PMID 30557390, 2018). "The tumors of the carriers of the MSH6 variants do not reveal MMR deficiency and TTN is known to harbor an excess of rare private variants, is mainly expressed in cardiac and skeletal muscle, and is associated with cardiomyopathies (MIM: 188840)." (PMID 26901136, 2016).
hereditary tumor syndrome (3 papers, 2019 to 2023). "Remarkably, 20% (5/24) of the patients with proven hereditary tumor syndrome and isolated loss of PMS2 or MSH6 were microsatellite stable (MSS) by PCR." (PMID 37874379, 2023).
leiomyosarcoma (3 papers, 2005 to 2022). An uncommon, aggressive malignant smooth muscle neoplasm, usually occurring in post-menopausal women.
medullary thyroid cancer (3 papers, 2016 to 2017).
mesothelioma (3 papers, 2022 to 2023). A usually malignant and aggressive neoplasm of the mesothelium which is often associated with exposure to asbestos. "Upon somatic NGS analysis of both the proband’s (II-3) and her brother’s (II-2) tumor samples, we identified a second variant: p.Arg1076His in MSH6 (48% VAF in the proband’s mesothelioma and RCC; 25% VAF in her brother’s mesothelioma)." (PMID 35885614, 2022).
metastatic prostate carcinoma (3 papers, 2018 to 2024). A carcinoma that arises from the prostate gland and has spread to other anatomic sites.
ovarian tumors (3 papers, 2018 to 2025). "Immunohistochemistry analysis was performed in the ovarian tumor of the patient and showed loss of MSH6 expression." (PMID 33008098, 2020). "In this cohort of breast and ovarian tumors, four rare variants in MSH6, one variant in RAD50, one variant in MRE11A, and two variants in RAD51 have been identified." (PMID 30283497, 2018).
pediatric cancer (3 papers, 2017 to 2020).
prostate adenocarcinoma (3 papers, 2022 to 2024).
rectal adenocarcinoma (3 papers, 2021 to 2023).
Stomach adenocarcinoma (3 papers, 2021 to 2023).
xeroderma pigmentosum (3 papers, 2017 to 2025). Xeroderma pigmentosum (XP) is a rare genodermatosis characterized by extreme sensitivity to ultraviolet (UV)-induced changes in the skin and eyes, and multiple skin cancers.
adrenal carcinoma (2 papers, 2022 to 2023). A carcinoma involving a adrenal gland.
B cell lymphomas (2 papers, 2010 to 2021).
Breast tumor (2 papers, 2018 to 2025).
cervical squamous cell carcinoma (2 papers, 2021 to 2024). A squamous cell carcinoma arising from the cervical epithelium. "The p.Phe1088LeufsTer5 frameshift variant in the MSH6 gene at genomic coordinate chr2:48030639 was identified in a patient born in 1962 with moderately differentiated invasive squamous-cell cervical cancer (stage IIb T2bN1M1nod grade IV), which was diagnosed in November 2021." (PMID 39595021, 2024).
chordoma (2 papers, 2023 to 2025). Chordomas are rare malignant tumors arising from embryonic remnants of the notochord in axial skeleton. "The most common mutations in pediatric chordoma cases were MRE11, FANCA, and MSH6, each individually appearing in two of the pediatric samples." (PMID 39941902, 2025).
colorectal polyps (2 papers, 2022). "Diagnoses of additional colorectal polyps developed by these two carriers of the MSH6 variant alone during the course of this study are detailed below." (PMID 36612224, 2022).
Crohn disease (2 papers, 2020 to 2021). A gastrointestinal disorder characterized by chronic inflammation involving all layers of the intestinal wall, noncaseating granulomas affecting the intestinal wall and regional lymph nodes, and transmural fibrosis.
desmoid tumor (2 papers, 2021 to 2024). A desmoid tumor (DT) is a benign, locally invasive soft tissue tumor associated with a high recurrence rate but with no metastatic potential. "In a small series of patients with desmoid tumors, disease-causing variants were identified in CHEK2, ERCC5, BLM, MSH6, and PALB2; however, none of these genes has been shown to be associated with increased risk of having desmoids." (PMID 38540414, 2024).
duodenal adenocarcinoma (2 papers, 2022 to 2026). A carcinoma that arises from glandular epithelial cells of the duodenum.
Huntington disease (2 papers, 2016 to 2024). Huntington disease (HD) is a rare neurodegenerative disorder of the central nervous system characterized by unwanted choreatic movements, behavioral and psychiatric disturbances and dementia.
hyperplastic polyp (2 papers, 2011 to 2022). A polyp found mainly in the stomach and colon. "MSH-6 frequently showed weak staining in 47 (28%) of the hyperplastic polyps analysed." (PMID 22312515, 2011).
inflammatory bowel disease (2 papers, 2017 to 2024). A spectrum of small and large bowel inflammatory diseases of unknown etiology. "In addition, the KEGG pathways enriched in the MSH6 low expression group were involved in multiple immune-related diseases, such as inflammatory bowel disease and asthma, and were also related to T cell differentiation and natural killer cell-mediated cytotoxicity." (PMID 38390329, 2024).
intestinal tumor (2 papers, 2012 to 2020).
intrahepatic cholangiocarcinoma (2 papers, 2019 to 2023). A carcinoma that arises from the intrahepatic bile duct epithelium in any site of the intrahepatic biliary tree.
liver cancer (2 papers, 2020 to 2021). An epithelial or non-epithelial malignant neoplasm that arises from the liver. "Meanwhile, MSH6’s high expression was also linked with poor PFS (P=0.0036), OS (P=0.012) and RFS (Relapse-free survival) (P=0.0034) prognosis of liver cancer patients." (PMID 34941572, 2021).